RNF144B (ring finger protein 144B)
Diseases named in the same sentence as RNF144B in open-access papers (continued):
Sharing a sentence is not in itself a finding about the gene and the disease.
cancer (6 papers, 2018 to 2025). A tumor composed of atypical neoplastic, often pleomorphic cells that invade other tissues. "Beyond contributing to the DNA double strand break repair, RNF144B deficiency induced chromosomal instability, a clear hallmark of aggressive and refractory cancers." (PMID 38685100, 2024). "These could indicate that cancer cells that are deficient for RNF144B have reduced sensitivity to drugs that specifically target the cell cycle, CIN or induce DNA damage." (PMID 38685100, 2024). "Intriguingly, this E3 ligase exhibits cancer-specific proteomic dysregulation – while maintaining comparable mRNA levels in normal and malignant endometrium, RNF144B protein expression is exclusively detected in endometrial carcinoma specimens." (PMID 40756570, 2025). "This highlights the pivotal role of RNF144B in cancer cell proliferation and transformation across various contexts." (PMID 38685100, 2024). "As a result, the up-regulation of RNF144B predicted cancer cell resistance against docetaxel and asparaginase." (PMID 36497225, 2022). "It was also found that Apoptin induces the expression of RNF144B, leading to degradation of ΔNp73 and activation of the pro-apoptotic target PUMA, which eventually results in cancer cell death." (PMID 40756570, 2025). "Previous studies have reported that RNF14, RNF31, RNF144B, RNF216 and ARIH1 mainly play carcinogenic roles, while ARIH2 and PARK2 generally play anticancer roles in malignant tumors." (PMID 35732617, 2022). "The negative correlation of RNF144B expression and aneuploidy showed to be significant too when human TCGA Pan-Cancer data were analyzed." (PMID 38685100, 2024).
infection (2 papers, 2024 to 2025). The state of being infected such as from the introduction of a foreign agent such as serum, vaccine, antigenic substance or organism. "Moreover, Rnf144b−/− mice exhibited a higher survival rate upon EMCV infection compared with wild-type mice." (PMID 39285245, 2024). "However, the expression of the RNF144B gene in pigs infected with the PRRSV can influence IFN production and function, facilitating the establishment of infection." (PMID 40284797, 2025).
infectious disease (1 paper, 2025). A disorder directly resulting from the presence and activity of a microbial, viral, or parasitic agent in humans. "In addition to being associated with tumors, RNF144A and RNF144B play important roles in neurological and infectious diseases." (PMID 40756570, 2025).
RNF144B also shares sentences with these, for which no sentence is quoted: Anxiety (1 paper); benign ovarian tumor (1); blood cancers (1); colorectal cancer (1); endometrial tumours (1); hepatocellular carcinoma (1); neuroblastoma (1); polycystic ovary syndrome (1); stomach cancers (1).